IL4 (interleukin 4)
Diseases named in the same sentence as IL4 in open-access papers (continued):
Sharing a sentence is not in itself a finding about the gene and the disease.
colitis (continued). "Thus S. mansoni soluble egg antigen (SEA) or cercariae exposure were shown to significantly attenuate trinitrobenzene sulfonic acid (TNBS)-induced or DSS-induced colitis in mice by enhancing IL-4 and IL-10 expression, decreasing INF-γ levels, or through induction of F4/80+ macrophages." (PMID 25879741, 2015). "Moreover, our current data also confirmed the effects of IL-4 on experiment colitis." (PMID 24314293, 2013). "paracasei L9 expressing Amuc_1100 protein, mRNA levels of pro-inflammatory cytokines (IL-6, TNF-α, and IL-1β) and anti-inflammatory cytokines (IL-4 and IL-10) were measured in colon tissues of DSS-induced colitis mice." (PMID 41515240, 2025). "The extract downregulated pro-inflammatory cytokines (IL-4, IFN-γ, IL-17, and TGF-β) and upregulated the level of the anti-inflammatory cytokine IL-10, significantly reducing the severity of colitis and improving colonic morphology." (PMID 40417008, 2025). "The levels of IL-4, IL-5, IL-17, and CCL11 were increased in the TA-administered colitis group compared with the unadministered colitis mice, but this increase was not statistically significant." (PMID 40333150, 2025). "In the context of OXA-induced colitis, KGM administration resulted in a marked reduction in the levels of critical inflammatory cytokines, specifically interleukin-4 (IL-4) and interleukin-13 (IL-13)." (PMID 40061034, 2025). "Bifidobacterium adolescentis ameliorated DSS-induced colitis by reducing TNF-α, IL-1β, and IL-6 levels and increasing IL-10 and IL-4 levels." (PMID 38540864, 2024). "In this study, after administering Ento-PB to rats with OXZ-induced colitis, the expression levels of IL-13 and TNF-α significantly decreased, while the expression levels of IL-4, IL-10, and EGF sharply increased." (PMID 39230095, 2024). "The results showed increased populations of CD4+ IFN-γ+ Th1 cells, CD4+ IL-4+ Th2 cells, and CD4+ IL-17+ Th17 cells in the DSS-induced colitis mice." (PMID 39595338, 2024). "Anti-inflammatory cytokines (such as IL-4, IL-10, IL-22, etc.)can inhibit the proliferation of TH17 and TH2 cells and intestinal wall disorders, thus alleviating colitis in mice." (PMID 37240380, 2023). "The result of our study was that the concentration of IL-2 and IL-4 was lower and the level of INF-γ and IL-17 was higher in the colon tissue of colitis mice." (PMID 37205093, 2023). "The study indicated that, a large number of proinflammatory factors (IFN-γ, IL-1β, IL-6, and TNF-α) were produced in the serum and colonic tissues after colitis was induced by DSS in mice, while the anti-inflammatory factors (IL-10 and IL-4) decreased." (PMID 36159803, 2022). "In the case of the anti-inflammatory cytokine IL-4, the levels were significantly (p < 0.05) low in the colonic homogenate of the TNBS colitis mice group (49.1 ± 3.20 pg/mL) compared to the non-colitis group (108.9 ± 8.2 pg/mL)." (PMID 35565934, 2022). "The increased IL-1b and TNF serum levels and enhanced HIF-1 and IL-10 expression in colitis mice were suppressed by CYN therapy, and the treatment facilitated IL-4, CCL2, and PPARγ expression." (PMID 36278202, 2022). "On the contrary, the expression of anti-inflammatory factors IL-4, IL-10, TGF-β and Foxp3 were significantly declined in the colitis group compared to the healthy mice." (PMID 35372817, 2022). "The murine interleukin-4 treated macrophage (MIL4) exerts anti-inflammatory and pro-healing effects and has been shown to reduce the severity of chemical-induced colitis." (PMID 34691050, 2021). "Although there are no direct reports of compounds from Polygalae Radix and Poria on the regulation of central neuronal inflammation, senegenin in Polygalae Radix et Rhizoma can reduce the symptoms of colitis by regulating IFN-γ and IL-4." (PMID 33790789, 2021).
colitis (continued). "The relative gene expressions of IFNγ, IL4, and STAT6 were significantly higher in the HA group in comparison to all groups with colitis (p < 0.01 for all comparisons with HA, with the exception of IL4: AC vs. HA, p < 0.05)." (PMID 33499240, 2021). "KM1608 significantly attenuated the disease activity of dextran sodium sulfate-induced colitis in mice and suppressed inflammatory mediators such as myeloperoxidase, proinflammatory cytokines (TNF-α and IL-6), and the Th2-type cytokine IL-4 in the colon." (PMID 32927852, 2020). "Schistosome egg diminished IFN-γ and enhanced IL-4 production from alpha CD3-stimulated mesenteric lymph node cells and spleen in TNBS-treated mice, thereby reducing colitis severity." (PMID 32153570, 2020). "Curcumin decreased the expression of Th1 cytokines (IL-12, IFN-γ, TNF-α) and increased that of Th2 cytokines (IL-4 and IL-10) in colon mucosa and thereby exerted therapeutic effects on TNBS-induced colitis." (PMID 32153570, 2020). "During colitis, TWD increased expression of Tnf by 2.5-fold, Il1b by 2.8-fold, Il4 by 4.8-fold, Il6 by 3.3-fold, Ifng by 3.8, and Il17f by 4.2-fold as compared to mice fed the AIN diet." (PMID 32093192, 2020). "Rg3-RGE + PT also up-regulated mice’s CD4+ cells, and the Th2 cytokine, IL-4, was identified as the target to protect mice from DSS-induced colitis." (PMID 33182623, 2020). "Functionally, Tfh cells are divided into Tfh1, Tfh2, Tfh10, Tfh17, Tfh21, and Tfr cell lineages, which respectively produce or express interferon (IFN)-γ, IL-4, IL-10, IL-17, IL-21, and forkhead box (FOX)P3, and these are closely related to colitis." (PMID 32581849, 2020). "In summary, our findings show that M2b macrophage exosomes attenuate disease activity, up-regulate Treg cells and IL-4, and reduce pro-inflammatory cytokine (IL-1β, IL-6, and IL-17A) production in mice with DSS-induced colitis." (PMID 31749791, 2019). "In rats with colitis rats treated with SSW, expression of IFN-γ, IL-1β, and IL-17 was suppressed, and expression of IL-4 was increased." (PMID 30894816, 2019). "As an anti-inflammatory cytokine, IL-4 inhibited inflammation in IBD patients and induced a Th2-type immune response in the mice with colitis." (PMID 31749791, 2019). "Obvious hyperemia and inflammatory cells infiltration were found in the colitis control groups accompanied with higher proinflammatory cytokines (IL-6 and TNF-α) and lower anti-inflammatory cytokines (IL-4 and IL-10)." (PMID 29785192, 2018). "Upon TWE stimulation during DSS-induced colitis, the frequencies of both Th1 and Th17 cells were significantly diminished in both the spleen and MLN, whereas IL4-producing Th2 cells were remarkably increased in the MLN." (PMID 28877696, 2017). "The data obtained indicate that IL-4Rα – and by inference IL-4 signaling – is required in both recipient and donor for HD-DCs to block DNBS-induced colitis." (PMID 28094779, 2017). "In line with increased IL-4 expression in IBDs described by other reports, we also observed an increased IL-4 expression in DSS-induced colitis." (PMID 28316599, 2017). "IL-9-producing type I NKT cells protect against DSS-induced colitis through IFN-γ and IL-17A suppression, as well as IL-10 and TGF-β upregulation, depending on IL-4 production by type I NKT cells." (PMID 28095507, 2017). "Moreover, these haplotypes in the IL-4 gene have significant effects on the response of immune cells to gram-negative bacteria, which may provide significant information for other conditions involving host-microbial interactions, such as colitis and sepsis." (PMID 28114408, 2017). "Since it was found to be capable of suppressing increased IL-17, and enhancing decreased IL-4 expressions, a characteristic of dextran sulfate sodium (DSS)- induced colitis, and presented a partial protection against DSS-induced colitis in mice." (PMID 27483999, 2016).
colitis (continued). "Intragastric administration of L. lactis MG1363 FnBPA+ (pValac::dts::IL-4) was able to decrease the severity of colitis, with animals showing decreased levels of IL-12, IL-6 and MPO activity; and increased levels of IL-4 and IL-10." (PMID 27576902, 2016). "In line with this, we found that Th17 (CD4+IL-17A+) and Th2 (CD4+IL-4+ and CD4+ IL-5+) obviously decreased in IL-21RKO mice with DSS-induced colitis." (PMID 27545302, 2016). "In this study, exogenous IL-1β reduced expression of colonic Th2 cytokines (IL-4 and IL-13) and improved OXA-induced colitis, while exogenous IL-18 also reduced severity of the colitis but without affecting expression of Th2 cytokines." (PMID 27966619, 2016). "The Th1 transcription factor T-bet plays a critical role in the development of Th1-driven colitis due to the high expression levels of IFN-γ, while GATA3 is an essential master regulator of Th2 cells for the induction of IL-4, IL-5, and IL-13." (PMID 26347453, 2015). "In this study, we investigated the effects of IL-4 or/and IL-10 gene therapy on TNBS-induced murine colitis." (PMID 24314293, 2013). "pcDNA3.0 carrying murine IL-4 or IL-10 cDNA was encapsulated with LipofectAMINE 2000 and intraperitoneally injected into mice with TNBS-induced colitis." (PMID 24314293, 2013). "To assess the effects of IL-4 or/and IL-10 expression on treatment of TNBS-induced murine colitis, we intraperitoneally injected these plasmids into mice and then detected these transgenic expressions in murine colon tissues using qRT-PCR." (PMID 24314293, 2013). "To further confirm the therapeutic effect of IL-4 and IL-10 gene therapy, we performed qRT-PCR analysis of their expression in TNBS-induced murine colitis tissues." (PMID 24314293, 2013). "This study further investigated the effect of IL-4 (IL-4), IL-10 and their combination on treatment of trinitrobenzenesulfonic acid (TNBS)-induced murine colitis." (PMID 24314293, 2013). "We injected intraperitoneally plasmids carrying IL-4 or/and IL-10 cDNA into mice with TNBS-induced murine colitis and tested the effects of transgenic expression on TNBS-induced murine colitis." (PMID 24314293, 2013). "Colons and mesenteric lymph nodes were harvested 7 days after the induction of colitis, and the expression of IFN-γ, IL-6, IL-17, IL-4, and IL-10 mRNA was quantified by real-time PCR." (PMID 22479648, 2012). "Those that were upregulated by 1 log fold or higher include IL-9, IL-13, IL-4, IL-17A, IL-5, IL-24, IFN-γ, IL-10, IL-11, and IL-27, many of which are known cytokines involved in the pathogenesis of colitis." (PMID 21365015, 2011). "Also, sinapic acid reduces serum levels of proinflammatory cytokines (TNF-α, IL-1β, IL-6, IL-17α, IL-18, and interferon (IFN)-γ) and increases anti-inflammatory cytokines (IL-4 and IL-10) in Kunming mice with DSS-induced colitis." (PMID 38732594, 2024). "Moreover, in an oxazolone-induced colitis model, KSI-6666 inhibited intestinal inflammation and up-regulated IL-4 protein levels in the whole intestine." (PMID 39030171, 2024). "ES from the human hookworm Ancylostoma caninum, given to mice daily i.p. during chemically induced colitis, has been shown to exert a modest reduction in pathological scores as well as the inflammatory cytokines, IFN-γ, and IL-17, and also to raise IL-4 and IL-10 responses." (PMID 36855464, 2023). "Other studies report that resveratrol reduces inflammation in patients with UC to improve their quality of life and disease clinical colitis activity, and in animal models of IBD, where there are reduced pro-inflammatory markers (TNF-α, IFN-γ, IL-1β, IL-6, and IL-4) and DAI." (PMID 37660064, 2023). "Therefore, this research assessed the role of Dioscin on macrophage polarization in vitro and in vivo and its molecular mechanism using the DSS‐induced colitis model in mice and RAW264.7 cells induced by lipopolysaccharide (LPS)/IL‐4." (PMID 35524480, 2022).
colitis (continued). "Among others, IL-4 and IL-13 are key effector cytokines in human UC and DSS-induced murine colitis." (PMID 36558966, 2022). "Nevertheless, the extent of macrophage infiltration was significantly decreased in mice given IL-4 neutralizing antibodies, without induction of colitis." (PMID 35442154, 2022). "M2 macrophage-derived exosomes upregulated Treg cells and IL-4, reduced the production of the proinflammatory cytokines IL-1β, IL-6 and IL-17A, reduced the severity of DSS-induced colitis in mice, and played a protective role in colitis." (PMID 36045437, 2022). "iNKT cells in the MLN display IL4-producing NKT2 phenotypes and could suppress DSS-induced colitis upon stimulation with orally administered α-galactosylceramide." (PMID 36499642, 2022). "Of note, the T cell response to the colitis process was totally blunted in the treated group, an effect evidenced across different T cell subpopulations, such as cytotoxic CD8+ T cells, Th1 (CD4+IFNg+), Th2 (CD4+IL4+), Th17 (CD4+IL17+), and Tregs (CD4+FoxP3+)." (PMID 34072532, 2021). "While we did not pursue the mechanism of the protection against colitis, the similarities in the splenic response at 4- and 8-dpi imply a common mode of action involving IL-4 and IL-10 signaling in the blockade of colitis, as we previously determined." (PMID 34451458, 2021). "Taken together, our data suggests that blocking IL-4/IL-13 signalling specifically on lysozyme M-positive macrophages and neutrophils has no significant influence in the onset of colitis." (PMID 32410852, 2020). "Interestingly, the colitis + TOE group showed high levels of both Th1 and Th2 transcription factors, but the secreted cytokine interferon (IFN)-γ and interleukin (IL)-4 remained unchanged and somewhat reduced." (PMID 33092149, 2020). "Remarkably increased IFNγ was detected not only in DSS-mediated colitis but also in E.coli O160:H7 colonized colon tissues as compared with their control mice, whereas other anti-inflammatory cytokines such as IL-4 did not significantly change." (PMID 31707260, 2019). "Therefore, the production of IL-4 and IL-13 in the colonic homogenate of rats was measured to study changes in the OXZ-induced colitis model." (PMID 31878303, 2019). "In line with observations from human WAS patients WAS−/− mice develop T cell dependent, severe progressive colitis characterized by both infiltration of neutrophils and lymphocytes and enhanced levels of IFN-γ, IL-4, and IL-13 by six months of age (50% fatality rate)." (PMID 31174293, 2019). "Significantly lower number of IL-10-, IL-4- and TGF-β-producing M2 macrophages infiltrated colons of DSS-treated Gal-3−/− animals 28 days after initial administration of DSS, which resulted in aggravation of DSS-induced colitis." (PMID 31336879, 2019). "We observed lower IL‐4 expression in p38α‐ΔMC mice compared to WT mice, both during DSS‐induced colitis and in the tumors, and given that IL‐4 is a major IGF‐1 inducer, it could further contribute to the decreased levels of IGF‐1 signaling in p38α‐ΔMC mice." (PMID 29907597, 2018). "Furthermore, it has been reported that the DSS-induced colitis model is characterized by increased serum levels of IL-6, IL-17, and TNF-α and decreased levels of IL-4 and IL-10." (PMID 30393231, 2018). "PEG2, rather than IL-4 or IL-13, was found in this study to play a critical role in potentiating the anti-inflammatory M2 phenotype in the early stage of colitis in miR-155−/− mice." (PMID 29774026, 2018). "The plasma concentrations of IL-17, KC, IL-1a and IL-4 were significantly increased in the sedentary mice with colitis fed a SD as compared to the respective values obtained in the sedentary mice without colitis fed a SD (p < 0.05)." (PMID 28425943, 2017). "In contrast to HD-DCs, adoptive transfer of IL-4 AADCs did not affect the outcome of DNBS-induced colitis as assessed by macroscopic and histopathology damage scores, and did not induce IL-4 or IL-10 in the spleen." (PMID 28094779, 2017).
colitis (continued). "In accordance with previous studies, our data also showed that there was an increased IL-4 level in DSS-induced colitis (data not shown)." (PMID 28316599, 2017). "Contrary to WT HD-DCs, IL-10−/− HD-DCs were unable to attenuate the severity of colitis, nor were they able to drive splenic IL-4 or IL-10 in recipients." (PMID 28094779, 2017). "Levels of TNF-α, IL-4 and IL-6 mRNA were significantly increased in the DSS model group compared with the healthy control group, indicating that DSS significantly increased intestinal inflammation in the DSS-induced colitis mouse model." (PMID 29162986, 2017). "Treatment of DCs with IL-4 evokes an alternatively activated phenotype, but adoptive transfer of these cells did not affect the outcome of colitis." (PMID 28094779, 2017). "The use of IL-4Rα−/− HD-DCs highlighted the reciprocity in the regulation of IL-4 and IL-10 production and the inhibition of colitis, since splenocytes from mice given these cells displayed no increase in IL-4 or IL-10." (PMID 28094779, 2017). "Then, it was transformed into the invasive strain L. lactis MG1363 FnBPA+ so that the therapeutic potential of this new construction, L. lactis MG1363 FnBPA+ (pValac::dts::IL-4), could be evaluated in the acute TNBS-induced mouse model of colitis." (PMID 27576902, 2016). "The level of Th1 cytokine-IFN-γ was significantly higher, but the levels of Th2 cytokine-IL-4, IL-5 or IL-13, and Th17 cytokine-IL-17A were greatly lower in colonic LP of IL-21RKO mice after DSS-induced colitis as compared with those in C57BL/6 mice (**P < 0.01 or ***P < 0.001)." (PMID 27545302, 2016). "Thus, Th2-like immunity characterized by the productions of IL-4 and IL-5 was impaired, whereas Th1-like immunity capable of producing IFN-γ was enhanced in DSS-induced colitis model in IL-21RKO mice." (PMID 27545302, 2016). "IL-4 levels are usually reduced both in CD and the TNBS-induced model of colitis." (PMID 27576902, 2016). "Moreover, our results also showed significantly increased transcriptional levels of IL-4 and IL-10 in the colon tissues of ERC-treated colitis mice compared to untreated colitis mice." (PMID 25475342, 2014). "Notably, ERCs attenuated colitis with significantly reduced DAI, decreased levels of intra-colon IL-2 and TNF-α, but increased expressions of IL-4 and IL-10." (PMID 25475342, 2014). "The Th2 cytokines IL-4 and IL-13 were apparently boosted in MLN and spleen lymphocytes of mice treated with T. spiralis AES in this study, but not significantly in treated mouse colons that represents a local response to DSS-induced colitis." (PMID 24788117, 2014). "The anti-colitis efficacy of a T. versicolor extract has also been demonstrated in an experimental colitis mice model, in which the oral administration of the extract suppressed the gene expression of STAT1, STAT6, IL-4, and IFN-γ." (PMID 24019869, 2013). "In the current study, we investigated the effects of IL-4 or/and IL-10 gene therapy against TNBS-induced murine colitis and found that the liposome-mediated combination gene therapy had a significant efficacy in treatment of TNBS-induced murine colitis." (PMID 24314293, 2013). "Analyses of specific T-cell regulatory cytokines (TNF-α, IL-4, IFN-γ, IL-17, TGF-β, IL-12) revealed that WCHF treatment can suppress the Th1 and Th17, but not Th2, responses in colon tissues and dendritic cells of DSS-induced colitis mice." (PMID 23734189, 2013). "Specifically, treatment of mice with IL-4 or IL-10 resulted in a marked improvement in the histological appearance of the distal colon and suppression of Th1-cell type cytokines, such as IFN-γ, TNF-α and IL-6 in TNBS-induced murine colitis." (PMID 24314293, 2013). "IL-4, IL-10 and INF-y concentrations (ρg/mL), MPO activity (U/mg) in the colon and DNA damage levels (tail moment/100 cells isolated from colon) of DSS-induced colitis rats fed Control, Fish or Soybean/Fish diet." (PMID 20615224, 2010).